SPANXN2 (SPANX family member N2)
Synonyms: SPANX-N2; CT11.7
Tractability: No criterion of Open Targets' tractability assessment is met for any kind of drug.
Gene: Protein-coding gene on chromosome X (143,711,955 to 143,720,752, reverse strand). Ensembl gene ENSG00000268988.
Subcellular location (Human Protein Atlas): Nucleoplasm; Nucleoli fibrillar center
Gene Ontology:
Molecular function: protein binding
Homologues: Orthologues: macaque SPANXN2 (78% identical), chimpanzee SPANXN2 (61% identical). Paralogues in human: SPANXN3 (60% identical), SPANXN1 (29% identical), SPANXN5 (28% identical), SPANXN4 (27% identical).
Diseases named in the same sentence as SPANXN2 in open-access papers:
SPANXN2 is named in the same sentence as 3 diseases in open-access papers, as found by Europe PMC text mining. Sharing a sentence is not in itself a finding about the gene and the disease. The quoted sentences say what the papers report.
testicular germ cell tumor (1 paper, 2020). A germ cell tumor arising from the testis. "The SPANXN2 is a gene expressed mainly in normal testis, but its role in testicular germ cell tumors (TGCTs) has yet to be investigated." (PMID 32612888, 2020).
tumor (1 paper, 2020). "Further studies are required to confirm that SPANXN2 suppresses tumor cell migration and colony formation by regulating EMT and AKT signaling pathways." (PMID 32612888, 2020). "In addition, further studies are required to confirm the molecular mechanisms by which SPANXN2 inhibited tumor cell migration by regulating the EMT and AKT/p-AKT signaling pathways." (PMID 32612888, 2020). "Our result showed that SPANXN2 inhibited TGCT cell migration, indicating that SPANXN2 is an inhibitor of tumor metastasis." (PMID 32612888, 2020). "Similar to our study, SPANXN2 inhibited the migration of TCGT cells, suggesting that SPANXN2 might be a tumor suppressor gene in TGCT and related to the poor prognosis of TGCT patients." (PMID 32612888, 2020).
SPANXN2 also shares sentences with these, for which no sentence is quoted: pituitary adenomas (1 paper).